ESR1 (estrogen receptor 1)
Diseases named in the same sentence as ESR1 in open-access papers (continued):
Sharing a sentence is not in itself a finding about the gene and the disease.
Hernia (5 papers, 2009 to 2025). "We analyzed LAM from men undergoing hernia surgery to examine E2/ESR1-mediated mRNA and protein expression and associated histological changes in human inguinal hernias." (PMID 39903526, 2025). "We further characterize LAM fibrosis through multiomics analyses of E2/ESR1 action on the HAFs to better understand molecular mechanisms underlying hernia formation." (PMID 39903526, 2025). "Furthermore, both pharmacologic inhibition and genetic ablation of ESR1 in the LAM fibroblasts of male Aromhum mice completely prevented LAM fibrosis and hernia development, highlighting the importance of fibroblast-specific E2/ESR1 signaling in causing hernias." (PMID 40504614, 2025). "To discern the impact of ESR1 signaling on LAM HAFs and hernia development, we engineered a fibroblast-specific ESR1 knockout in Aromhum mice (fEsr1–/– Aromhum) by cross-breeding floxed ESR1, PDGFRA-cre, and Aromhum mice." (PMID 39903526, 2025). "This selective upregulation of the TGF-β pathway mimics the increased proliferation seen in an acute injury response, whereas inhibiting E2/ESR1 signaling via fulvestrant suppresses this mechanism, promoting hernia regression and regeneration pathways." (PMID 39903526, 2025). "In contrast, ESR1 deletion and fulvestrant treatment provide more comprehensive and stronger inhibition of ESR1 action, leading to more pronounced effects on hernia regression." (PMID 39903526, 2025). "The percentage of HAFs marked by expression of PDGFRA and ESR1 was significantly lower in the hernia-free fEsr1–/– Aromhum mice compared with the positive control herniated fEsr1+/+ Aromhum mice (1.8% vs. 32.3%)." (PMID 39903526, 2025). "To ascertain the specificity of hernia regression to ESR1, we used methyl-piperidino-pyrazole (MPP), an ESR1-selective antagonist, in Aromhum mice with large scrotal hernias." (PMID 39903526, 2025). "Our study adds to these findings by demonstrating that E2/ESR1 induces profibrotic genes and pathways that can propagate hernia pathology." (PMID 39903526, 2025). "The use of PDGFRA-cre mice facilitated the selective ablation of ESR1 in PDGFRA+ FAPs, underscoring the sufficiency of these cells in the fibrotic processes associated with hernias." (PMID 39903526, 2025). "Single-cell RNA sequencing (scRNA-Seq) analysis of LAM further delineated a hernia-associated fibroblast (HAF) cluster in Aromhum mice, marked by elevated ESR1 expression." (PMID 39903526, 2025). "Expression of ESR1 and the cell proliferation marker Ki67 were observed in a strikingly higher number of cells in hernia site LAM compared with adjacent healthy muscle." (PMID 39903526, 2025). "Next, we demonstrated significantly increased in vivo mRNA expression of the key E2/ESR1-target genes using the tissues of Aromhum mice, which developed large hernias for 12 weeks." (PMID 39903526, 2025). "While the Aromhum hernia model has been used previously to establish the role of E2/ESR1 signaling in LAM fibroblast activation, this study furthers our understanding of hernia pathogenesis by implicating P4/PGR signaling as an important downstream regulator of E2/ESR1-induced LAM fibrosis." (PMID 40504614, 2025). "Thus, we hypothesize that HAFs, a subset of PDGFRA+ fibroblasts (FAPs), possibly activated by E2/ESR1 signaling, play an essential role in hernia formation in Aromhum mice." (PMID 39903526, 2025). "Effect of E2/ESR1-induced PGR expression on LAM fibroblast proliferation in Aromhum mice and human hernia tissue." (PMID 40504614, 2025). "Our findings, along with the positive correlation between ESR1, PGR, and Ki-67 expression in human stromal hernia tissue, highlight both a role for P4/PGR signaling and a potential use for PGR antagonists in men." (PMID 40504614, 2025).
hip fracture (5 papers, 2009 to 2026). Traumatic or pathological injury to the hip in which the continuity of either the femoral head, femoral neck, intertrochanteric or subtrochanteric regions is broken. "The association of the ESR1 PvuII (C>T) polymorphism and hip fracture was investigated in eight studies, with a total of 1,838 cases and 14,972 healthy controls." (PMID 24482673, 2013). "The association between the ESR1 XbaI (A>G) polymorphism and hip fracture was investigated only in four studies, with a total of 853 cases and 4,522 healthy controls." (PMID 24482673, 2013). "Two recent genome wide association studies (GWAS) have found that several loci in the 6q25 ESR1 region are associated with bone mineral density of the hip and spine, providing rapid insights into the genetic association between ESR1 gene and hip fracture risk." (PMID 24482673, 2013). "They investigated 1838 patients with hip fracture and 14,972 healthy controls and showed that the p allele of ESR1 might increase the risk of hip fracture, while the XbaI polymorphism remained non-associated with fracture risk." (PMID 31450614, 2019). "Subgroup analyses for the associations of ESR1 XbaI (A/G) with hip fracture risk." (PMID 24482673, 2013). "Subgroup analyses for the associations of ESR1 PvuII (C/T) with hip fracture risk." (PMID 24482673, 2013). "Therefore, we performed a meta-analysis of all eligible case-control studies associating hip fracture risk linked with gender and menopausal status in order to explicate the relationship between two common polymorphisms (PvuII and XbaI) in the ESR1 gene and hip fracture susceptibility." (PMID 24482673, 2013).
insomnia (5 papers, 2019 to 2025). A sleep disorder characterized by difficulty in falling asleep and/or remaining asleep. "The results from the PPI analysis show that the targets of VVO for the treatment of insomnia mainly involve MAOB, DRD2, MAOA, IL1B, PTGS2, HTR2A, SLC6A4, and ESR1." (PMID 40004189, 2025).
leiomyosarcoma (5 papers, 2014 to 2025). An uncommon, aggressive malignant smooth muscle neoplasm, usually occurring in post-menopausal women. "Specifically, genes such as PGR, TRIM22, BOK, NAALADL1, AFAP1L2, and ESR1 showed MSS values greater than 5 in uterine leiomyosarcoma samples." (PMID 38066476, 2023).
mood disorder (5 papers, 2019 to 2025). A cognitive disorder a disturbance in which the person's mood is hypothesized to be the main underlying feature. "For instance, genetic variations in the ESR1 gene, which encodes the estrogen receptor α (ERα), have been linked to altered susceptibility to mood disorders." (PMID 40282331, 2025). "The present findings suggest that differential manipulation of Esr1 and Esr2 in males and females might have potential applications for the treatment of mood disorders." (PMID 30863326, 2019).
osteonecrosis (5 papers, 2022 to 2025). A none disease characterized by death of bone tissue due to a lack of blood supply. "This study showed that ESR1 polymorphism in female patients with estrogen deficiency was associated with medication-related osteonecrosis." (PMID 37415765, 2023). "In the Dex-treated group, ESR1 expression was markedly diminished, consistent with disrupted bone homeostasis and increased osteonecrosis." (PMID 40149590, 2025). "This study highlights the therapeutic potential of salvigenin in glucocorticoid-induced osteonecrosis of the femoral head (GIOFH) through its multi-target mechanisms, particularly its modulation of ESR1-mediated pathways." (PMID 40149590, 2025). "The mechanism that polymorphisms of ESR1 affect osteonecrosis could not be investigated." (PMID 37415765, 2023). "This study explored the potential therapeutic role of salvigenin in glucocorticoid-induced osteonecrosis of the femoral head (GIOFH), focusing on its effects on oxidative stress, osteoblast viability, and osteogenic differentiation via the estrogen receptor alpha (ESR1)-mediated pathway." (PMID 40149590, 2025).
retinoblastoma (5 papers, 2012 to 2022). A malignant tumor that originates in the nuclear layer of the retina. "Hence, detailed analysis on the role of ESR1 in Rb tumors is highly warranted to unravel its role in Rb pathogenesis." (PMID 35359459, 2022). "Interestingly, the GEO2R and co-expression network analysis have identified three genes namely E2F3, ESR1, and UNC5D that are significantly deregulated by modified DNA methylation, mRNA and microRNA expression in Rb tumors." (PMID 35359459, 2022). "The expression of E2F3 and UNC5D were up-regulated and that of ESR1 was down-regulated in Rb tumor cells when compared to that in non-tumorigenic hTERT-RPE cells." (PMID 35359459, 2022).
uterine corpus endometrial carcinoma (5 papers, 2016 to 2025). A endometrial carcinoma (disease) that involves the body of uterus. "We observed similar features in the uterine corpus endometrial carcinoma dataset: the genes with the highest frequency included SOX17 and C3 (8%), PAX8, MME and ESR1 (7%)." (PMID 31879572, 2019).
acute kidney injury (4 papers, 2014 to 2026). Sudden and sustained deterioration of the kidney function characterized by decreased glomerular filtration rate, increased serum creatinine or oliguria. "The identification of β‐oestradiol and the estrogen receptor (ESR1) was of interest since acute kidney injury is less common and less severe in women than in men." (PMID 34626063, 2021).
alcohol (4 papers, 2014 to 2025). "The ESR1 SNPs rs6902771, rs11155819, rs6557171, rs2982683 and rs2982712 were shown to be jointly associated with alcohol dependency in the genetic subproject." (PMID 40730494, 2025).
anovulation (4 papers, 2012 to 2024). The absence of ovulation. "Previous research has demonstrated that female mice with ER-α (Esr1) gene knockout exhibit PCOS-like phenotypes, including polycystic ovaries, anovulation, and corpus luteum deficiency." (PMID 39765695, 2024).
endometrial endometrioid adenocarcinoma (4 papers, 2014 to 2025). A primary endometrial adenocarcinoma composed of neoplastic cells that form complex glandular patterns associated with budding and branching of the neoplastic glands. "The significant interest in overcoming ESR1 mutations for patients with resistance to aromatase inhibitors may ultimately provide new avenues for patients with these de novo alterations in uterine endometrioid carcinomas." (PMID 40981433, 2025). "Interestingly, we found that two of the 11 patients with uterine endometrioid carcinomas had alterations in ESR1, including two hotspot mutations at Tyr537 (Y537C and Y537N) and an alteration at Leu536 (L536R)." (PMID 40981433, 2025).
follicular thyroid cancer (4 papers, 2015 to 2020). "In the current follicular thyroid cancer study, extra thyroidal extension (p=0.036) and late stage disease (p=0.035) are associated with ESR1 methylation suggesting loss of its tumor-suppressor role." (PMID 27158284, 2015). "Together, in this study, RASSF1, DAPK1 and ESR1 suggest utility of methylation markers to molecularly differentiate follicular thyroid cancer subtypes for enhanced classification." (PMID 27158284, 2015).
glaucoma (4 papers, 2013 to 2025). Increased pressure in the eyeball due to obstruction of the outflow of aqueous humor. "The Rotterdam study found that polymorphisms (haplotype 1) of estrogen receptor-β (ESR2) were associated with an increased risk of open-angle glaucoma in males but not in females, while no haplotypes of estrogen receptor-α (ESR1) altered the risk of developing glaucoma in either sex." (PMID 34981287, 2023).
hyperandrogenism (4 papers, 2022 to 2024). Excessive secretion of androgens from the adrenal glands or gonads. "The conducted studies were aimed at determining the influence of three gene polymorphisms: ESR1 rs1884051, rs2077647 and rs30220314 on selected metabolic, hormonal and bone metabolism parameters in 80 young women with hyperandrogenization." (PMID 36385124, 2022). "The aim of the study was to assess the effect of estrogen receptor α gene (ESR1) polymorphisms on selected markers of bone metabolism and hormonal parameters in women with hyperandrogenism." (PMID 36385124, 2022).
influenza (4 papers, 2011 to 2026). An acute viral infection of the respiratory tract, occurring in isolated cases, in epidemics, or in pandemics; it is caused by serologically different strains of viruses (influenzaviruses) designated A, B, and C, has a 3-day incubation period, and usually lasts for 3 to 10 days. "Supporting evidence from animal studies shows that activation of estrogen receptor-1 in female mice reduces pulmonary levels of proinflammatory cytokines and chemokines, leading to improved outcomes following influenza infection." (PMID 40676907, 2025).
laryngeal squamous cell carcinoma (4 papers, 2015 to 2021). A squamous cell carcinoma that arises from the larynx. "A previous study by our group on laryngeal squamous cell carcinomas identified aberrant methylation of ESR1 as an independent predictor of late stage diagnosis (Stephen, Chen, Shah, Havard, & Kapke, 2010)." (PMID 27158284, 2015). "Laryngeal squamous cell carcinoma (LSCC) responds to 17β-estradiol via estrogen-receptor (ER, transcribed from ESR1) dependent mechanisms, but is not recognized as a hormonally responsive cancer." (PMID 32144339, 2020).
liposarcoma (4 papers, 2014 to 2016). A usually painless malignant tumor that arises from adipose tissue. "Comparative genomic hybridization (CGH) studies on copy number in dedifferentiated and pleomorphic liposarcomas have revealed gain in copy number of oncogenes, notably ESR1 (Estrogen receptor 1), a receptor in estrogen signaling." (PMID 25984907, 2015).
neuropathy (4 papers, 2016 to 2025). A disorder affecting the nervous system that manifests with pain, tingling, numbness, and/or muscle weakness. "It was observed that higher methylation within the estrogen receptor 1 (ESR1) gene was associated with neuropathy on the paclitaxel arm." (PMID 29038614, 2017). "Esr1 and Esr2 are expressed in both IHCs and OHCs, and they protect against neuropathy following acoustic trauma." (PMID 26881968, 2016).
oropharyngeal squamous cell carcinoma (4 papers, 2020 to 2024). "Recent studies have shown a correlation between estrogen receptor 1 (ESR1) expression and a more favorable survival for oropharyngeal squamous cell carcinoma (OPSCC), suggesting a potential role for estrogen receptor alpha (ERα) signaling in the development and maintenance of these tumors." (PMID 38279245, 2024).
postpartum depression (4 papers, 2018 to 2022). A type of clinical depression that occurs after childbirth. "In addition, preliminary studies have found that genetic variants in the Esr1 gene were associated with harsh parenting and could play a role in postpartum depression in human populations." (PMID 33560574, 2021). "ESR1 is an estrogen receptor that might be involved in the etiology of postpartum depression by regulating 5-hydroxytryptamine (5-HT) signaling." (PMID 36431060, 2022).
renal fibrosis (4 papers, 2022 to 2025). A final common manifestation of a wide variety of chronic kidney diseases characterized by glomerulosclerosis and tubulointerstitial fibrosis. "The core genes SRC, IGF1, RHOA, ESR1, EGFR and CDC42 may play a key role in the inhibition of the development and progression of renal fibrosis by diosgenin." (PMID 37179298, 2023).
vitiligo (4 papers, 2019 to 2024). Generalized well circumscribed patches of leukoderma that are generally distributed over symmetric body locations and is due to autoimmune destruction of melanocytes. "ESR1 has been reported as one of the proteins contributing to vitiligo susceptibility." (PMID 38659590, 2024). "It has also been reported that estrogen receptor 1 C/T polymorphism is associated with vitiligo." (PMID 32790741, 2020). "The five key target genes (AKT1, VEGFA, ESR1, IL2, and MPO) identified by the compound–target network were closely related to the pathogenesis and/or treatment of vitiligo." (PMID 38659590, 2024). "In the present study, our analysis suggested that KBL might be of therapeutic effects on vitiligo by affecting catecholamine metabolism, neurotransmitter degradation (MAOA and MAOB), and intracellular steroid hormone receptor signaling pathway (ESR1)." (PMID 31781265, 2019).
adenosarcoma (3 papers, 2017 to 2025). A low grade malignant neoplasm characterized by the presence of a benign epithelial component (tubular and cleft-like glands) and a low grade sarcomatous component that contains varying amounts of fibrous and smooth muscle tissues. "In our previous analysis of adenosarcomas, RNA‐sequencing revealed, for instance, fusion genes involving ESR1 and NCOA family members in two of six samples." (PMID 28267263, 2017).
adolescent idiopathic scoliosis (3 papers, 2019 to 2024). A scoliosis with no known cause arising in adolescent. "Previous studies found decreased ESR1 expression of concave paraspinal muscle progenitor cells could contribute to the initiation and progression of adolescent idiopathic scoliosis (AIS)." (PMID 39600965, 2024).
amenorrhea (3 papers, 2016 to 2024). The absence of menses in a woman who has achieved reproductive age. "A loss-of-function ESR1 mutation was identified in a woman without breast development, primary amenorrhea, a small uterus and multicystic ovaries." (PMID 38978624, 2024).
bile duct cancer (3 papers, 2012 to 2022). "For example, the study conducted by Park and colleagues, shows that the G allele of the ESR1-rs1801132 SNP was associated with increased risk of developing bile duct cancer (OR = 1.70, 95% CI 1.10–2.80, P = 0.07) compared with C allele." (PMID 36302831, 2022).
brain tumors (3 papers, 2015 to 2025). "We showed that CSF ctDNA is more representative of brain tumour genomic alterations than plasma and putative actionable gene mutations and CNA (that is, EGFR, PTEN, ESR1, IDH1, ERBB2, FGFR2) can be identified." (PMID 26554728, 2015).
cardiac ischemia (3 papers, 2020 to 2025). "ESR1 is well known to protect against myocardial ischemia/reperfusion injury by inhibiting MPTP openings." (PMID 36160433, 2022).
cataract (3 papers, 2009 to 2022). Partial or complete opacity of the crystalline lens of one or both eyes that decreases visual acuity and eventually results in blindness. "Four genes, including ESR1, MAPK14, CASP3, and AKR1B1, were shared between CS compound targets and cataracts' targets, indicating their possible anticataract action." (PMID 35860180, 2022). "Network analysis suggested that four shared targets may play crucial roles in the treatment of cataracts, including aldose reductase (AKR1B1), caspase-3 (CASP3), mitogen-activated protein kinase 14 (MAPK14), and estrogen receptor (ESR1)." (PMID 35860180, 2022).
chronic hepatitis B (3 papers, 2012 to 2023). "During the course of chronic hepatitis B progressing to end-stage liver disease, variant forms of ESR1 predominates and sometimes becomes the only form expressed." (PMID 22727021, 2012). "ESR1 was lowly expression in liver tissues from chronic hepatitis B induced HCC in the GSE121248 dataset." (PMID 35388301, 2022).
colon adenocarcinoma (3 papers, 2019 to 2025). "Methylation of the ESR1, MGMT, HPP1/TPEF, HLTF, and NGFR genes is associated with the onset of colon adenocarcinoma and occurs during the early stages of oncogenesis." (PMID 31852837, 2019).
cryptorchidism (3 papers, 2008 to 2024). The failure of one or both testes of a male fetus to descend from the abdomen into the scrotum during the late part of pregnancy. "In conclusion, our initial study showed that the association of INSL3 and ESR1 polymorphism with cryptorchidism in dogs seems to be unlikely." (PMID 30338045, 2018).
dilated cardiomyopathy (3 papers, 2020 to 2024). Cardiomyopathy which is characterized by dilation and contractile dysfunction of the left and right ventricles. "ESR1 has been shown to be upregulated in dilated cardiomyopathy, likely as a compensatory response, as ERα can aid in myocardial protection." (PMID 39363102, 2024).
Down syndrome (3 papers, 2013 to 2024). "Furthermore differences between ESR1 alleles correlates with an increased risk for AD in women with Down syndrome." (PMID 23803348, 2013).